KLK1 (kallikrein 1)
Diseases named in the same sentence as KLK1 in open-access papers (continued):
Sharing a sentence is not in itself a finding about the gene and the disease.
adenoma (2 papers, 2022 to 2025). A neoplasm arising from the epithelium. "On the other hand, the Apcmin/+ mouse model represents the process of adenoma carcinogenesis driven by gene mutations, which can be used to verify the prevalence and mechanism of KLK1 in non‐inflammation‐dependent colorectal tumorigenesis." (PMID 40859429, 2025). "The Klk1 gene was also observed to be associated with prolactin-secreting cells within human Gh1-secreting adenomas." (PMID 35180880, 2022). "Increased KLK1 expression led to decreased Mmp2 and Mmp9 levels and reduced adenoma formation, an effect inhibited by SSR240612." (PMID 40859429, 2025). "Endoscopy showed KLK1 treatment significantly improved adenoma occurrence, indicating KLK1 protects the gut and prevents inflammation‐cancer transformation via B1R." (PMID 40859429, 2025). "In the Apcmin/+ model, supplementation with KLK1 significantly inhibited adenoma formation, reduced epithelial dysplasia, and downregulated pro‐oncogenes such as Mmp2, Mmp9, Fap, Dcn, and Ctnnb1." (PMID 40859429, 2025). "In the colitis‐carcinoma transformation model, KLK1 supplementation reduced adenoma formation induced by AOM‐DSS, an effect inhibited by SSR240612." (PMID 40859429, 2025). "In this study, we detected the expression of KLK1 in serum and tissues of patients with ulcerative colitis, adenoma, and colorectal cancer." (PMID 40859429, 2025). "In two classic animal models of colorectal cancer, the AOM‐DSS‐induced inflammation‐cancer transformation model and the high‐fat diet‐induced Apcmin/+ adenoma carcinogenesis model, KLK1 expression was significantly downregulated." (PMID 40859429, 2025). "We performed SCENIC analysis through inflammation‐cancer transformation and Apcmin/+ adenoma carcinogenesis models, and hoped that a transcription factor that regulates KLK1 expression will be found." (PMID 40859429, 2025). "KLK1 administration significantly reduced adenoma incidence, but B1R inhibition attenuated this improvement." (PMID 40859429, 2025). "In summary, we used the AOM‐DSS‐induced colitis‐cancer transformation model to reveal the mechanism of action of KLK1 in inhibiting adenoma formation and maintaining intestinal homeostasis through a B1R‐dependent mechanism." (PMID 40859429, 2025). "In summary, we demonstrated that KLK1‐B1R plays a broad inhibitory role in colorectal tumor formation using two classic colorectal cancer models, the AOM‐DSS inflammation‐oncogenic transformation model and the Apcmin/+ adenoma carcinogenesis model." (PMID 40859429, 2025).
angioedema (2 papers, 2018 to 2019). Swelling involving the deep dermis, subcutaneous, or submucosal tissues, representing localized edema. "Speculatively, KLK-1 could also be a trigger for yet to be discovered forms of shock or angioedema with normal C1-INH." (PMID 30333824, 2018). "KLK-1 release from vascular or other cell types could be a trigger for ACE inhibitor-induced angioedema, a condition reportedly resistant to ecallantide and probably to the B2R antagonist icatibant." (PMID 30333824, 2018). "While plasma kallikrein has a central role in HAE-1, HAE-2, and angioedema due to acquired C1-INH deficiency, the role of KLK-1 and cellular elements (leukocytes, platelets) has not been ruled out in the initiation of kinin-mediated vascular disorders." (PMID 30333824, 2018). "KLK-1 is not usually mentioned as a mediator of angioedema states, despite its very effective action as a kinin-forming agent that is unaffected by HAE-1/2." (PMID 30333824, 2018). "KLK-1 is not a part of the contact system and its effect on iBK generation is not modified by HAE-1/-2, but its role is not excluded in other forms of angioedema or anaphylactoid states." (PMID 31133046, 2019).
asthma (2 papers, 2024 to 2025). "In the airways, elevated KLK1 activity has been detected in asthma patients, where it contributes to goblet cell metaplasia and mucus hypersecretion, hallmarks of airway obstruction." (PMID 41516101, 2025). "Also, the inhibitory monoclonal antibody DX-2300 targets KLK1 to treat diseases of the human airways, like asthma." (PMID 41516101, 2025). "In addition, KLK1 is involved in asthma pathogenesis with KLK3 and KLK14." (PMID 41516101, 2025).
autoimmune disease (2 papers, 2014 to 2015). A disorder resulting from loss of function or tissue destruction of an organ or multiple organs, arising from humoral or cellular immune responses of the individual to their own tissue constituents. "In autoimmune diseases and T1D, KLK-1 activity has been associated with both beneficial and detrimental effects." (PMID 25259810, 2014). "Kallikrein-1 has been implicated as an autoantigen in the IQI/Jic mouse model of SS, and earlier studies associated sialylation of tissue Kallikreins with autoimmune diseases." (PMID 26245278, 2015).
Autoimmunity (2 papers, 2017 to 2021). The occurrence of an immune reaction against the organism's own cells or tissues. "Further differentially expressed genes of interest are Klk1 and DNase1l3, that are both associated with autoimmunity." (PMID 34497606, 2021).
cardiac hypertrophy (2 papers, 2016 to 2018). "Given that KLK1 is also involved in cardiac hypertrophy, the expression of KLK1 in hypertrophic hearts was also examined." (PMID 26823023, 2016). "Nevertheless, the differences in KLK1 and KLK8 expression pattern in cardiac hypertrophy suggest that KLK1 and KLK8 might play different roles in this cardiac disorder." (PMID 26823023, 2016).
Cerebral ischemia (2 papers, 2015 to 2025). Restriction of arterial blood supply to the brain associated with insufficient oxygenation to support the metabolic requirements of the tissue. "In models of cerebral ischemia–reperfusion, KLK1 exhibits neuroprotective properties by upregulating the Nrf2 pathway and downregulating the TLR4/NF‐κB pathway." (PMID 41322027, 2025). "Recently, we demonstrated that KLK1 supplementation during cerebral ischemia can inhibit the excessive activation of KKS system induced by reperfusion injury, thereby reducing blood–brain barrier damage and protecting the neurovascular unit." (PMID 41322027, 2025).
chronic prostatitis (2 papers, 2021 to 2022). An infectious or non-infectious chronic inflammatory process that affects the prostate gland. "Assessment of inflammation degree also showed that KLK1 administration (EAPK group) significantly reduced the severity of prostatitis." (PMID 35154561, 2022). "Our next experimental plan is to use KLK1 administration on the testosterone-induced BPH rat model and chronic prostatitis rat model to study the interaction of KLK1 on hormones and inflammation-related mechanisms." (PMID 34007408, 2021). "Notably, KLK1 administration to normal rats (NCK group) did not affect their prostate pathological performance and that HOE140 blocking the KLK1/BK signaling pathway (EAPKH group) made the anti-inflammatory effect of KLK1 on prostatitis be canceled." (PMID 35154561, 2022). "KLK1 administration inhibited TGF-β-related fibrosis signaling pathways, increased the expression of eNOS as well as ameliorated hypoxia and oxidative stress, and suppressed the proangiogenic VEGF in prostatitis rats." (PMID 35154561, 2022).
colon cancer (2 papers, 2022 to 2025). "KLK1 expression was downregulated in both pancreatic and colon cancer in previous studies." (PMID 35974070, 2022). "Our findings support human translational relevance, with KLK1 levels being reduced in IBD patients with UC and further reduced in patients with colorectal low‐grade endothelial neoplasia and colon cancer, suggesting KLK1 dysregulation in IBD and potential opportunities for intervention using KLK1." (PMID 40859429, 2025).
diabetes (2 papers, 2024 to 2025). "The discrepancies in these observations may be attributed to variations in KLK1 expression levels at different stages of diabetes mellitus." (PMID 41322027, 2025).
fetal growth restriction (2 papers, 2025). A fetus that does not grow beyond the 10th percentile of conventionally accepted weight for gestational age. "In addition, lower urinary levels of histidine-rich glycoprotein (HRG) and kallikrein-1 (KLK1) suggest impaired angiogenesis and kallikrein–kinin signaling, processes implicated in pre-eclampsia and intrauterine growth restriction." (PMID 41614738, 2025).
gastric cancer (2 papers, 2016 to 2020). A primary or metastatic malignant neoplasm involving the stomach. "For example, KLK1 is proposed as the biomarker of gastric cancer due to the elevation of KLK1 levels in gastric neoplasm and the prevention of tumor growth in gastric cancer by inhibition of KLK1 activity with kallikrein-binding protein (KBP)." (PMID 32993568, 2020). "We examined the levels of KLK1–8 mRNAs compared with GAPDH mRNA in various gastric cancer cell lines using RT-PCR." (PMID 27863404, 2016).
ischemia (2 papers, 2011 to 2025). A hypoperfusion of the BLOOD through an organ or tissue caused by a PATHOLOGIC CONSTRICTION or obstruction of its BLOOD VESSELS, or an absence of BLOOD CIRCULATION. "The serine protease tissue kallikrein (KLK1), extensively expressed in various tissues, including the vasculature, provides numerous protective effects against ischemia and promotes healing responses." (PMID 41200935, 2025).
kidney stone (2 papers, 2024 to 2025). "The results showed that the AUC (area under the curve) values of KLK1 and MMP10 were 0.724 and 0.737, respectively, both exceeding 0.7, indicating their high diagnostic value in evaluating the progression of kidney stones." (PMID 39606015, 2024). "KLK1 and MMP10 were identified as potential diagnostic markers and key players in kidney stone progression." (PMID 39606015, 2024). "The analysis revealed an AUC value of 0.724 for KLK1 and 0.737 for MMP10, highlighting their substantial diagnostic value in evaluating kidney stone progression." (PMID 39606015, 2024). "Through machine learning algorithms, KLK1 and MMP10 were identified as optimal feature genes, significantly upregulated in kidney stone samples, with high diagnostic value." (PMID 39606015, 2024). "In the subsequent integration of machine learning algorithms, we identified two optimal feature genes—KLK1 and MMP10, and confirmed their significant upregulation in kidney stone samples." (PMID 39606015, 2024). "The expression levels of the two optimal feature genes, KLK1 and MMP10, were validated in 29 kidney stone samples and 33 normal samples." (PMID 39606015, 2024). "Given the potential importance of KLK1 and MMP10 in kidney stones, we further conducted gene set enrichment analysis (GSEA)." (PMID 39606015, 2024). "The results indicated a significant upregulation of KLK1 and MMP10 genes in kidney stone samples, suggesting their pivotal roles in kidney stone progression (p < 0.01)." (PMID 39606015, 2024).
Lung Diseases (2 papers, 2019 to 2025). "Nine of the family members, including KLK1, are expressed in the lung and have been implicated in various lung diseases—inflammatory respiratory diseases, viral infections, and cancers." (PMID 31727138, 2019). "In summary, KLK1 serves as a bimodal regulator, essential for maintaining blood pressure stability and significantly influencing lung disease pathophysiology." (PMID 41516101, 2025). "Genetic studies highlight a nuanced role for KLK1 in lung disease: certain polymorphisms appear to reduce the risk of onset of COPD, while lower KLK1 levels in established COPD may worsen outcomes upon viral infections." (PMID 41516101, 2025).
pancreatic cancer (2 papers, 2016 to 2022). "Surprisingly, in previous studies, it has been proved that all of our defined switch genes, including Lamc2, Klk1, Nqo1, Aox1, Tspan1, and Cxcl12, are closely associated with the pancreatic cancer’s progression." (PMID 35180880, 2022). "Besides, we have introduced two biologically relevant triplets, namely Klk1 and {Gh1, Cst3} and Lamc2 and {Dhps, Ccr7}, which may be specifically involved in the onset of pancreatic cancer." (PMID 35180880, 2022). "Furthermore, down-regulated mRNAs of the kallikrein peptidase family (Klk1, Klk1b3, Klk1b5) and the cholecystokinin receptor type A (CCKAR), and expression of cdh2 coding for N-cadherin as well as somatostatin discriminated pancreatic tumors from pancreatic controls." (PMID 27769070, 2016).
renal cell carcinoma (2 papers, 2024 to 2025). "Emerging evidence suggests potential associations with renal pathophysiology, like renal cell carcinoma (RCC), though its functional significance in the kidney remains less characterized compared with other kallikreins, such as tissue kallikrein (KLK1)." (PMID 40428321, 2025). "In terms of renal cell carcinoma (RCC), clinical experimental studies have proven that some KLKs, such as KLK1, KLK3, KLK6, KLK7, and KLK15, are differentially expressed in different subtypes of RCC, and KLK6 has predictive value in RCC." (PMID 39116105, 2024).
thyroid cancer (2 papers, 2015 to 2018). "Additionally, KLK3 (human denotation of KLK1 in mouse) is among the involved molecules in all groups that show an impact on thyroid cancer signalling." (PMID 26492889, 2015).
type 1 diabetes (2 papers, 2023 to 2024). "In type 1 diabetes models, virus-mediated expression of KLK1 or recombinant KLK1 administration has been shown to decrease blood glucose and delay onset of the disease." (PMID 37358498, 2023). "It is noteworthy that, regardless of whether in the high expression group of KLK1 or MMP10, the type I diabetes pathway was significantly enriched." (PMID 39606015, 2024).
acute tubular necrosis (1 paper, 2011). "Previously, we have reported that urinary KLK1 excretion was diminished in renal allograft recipients with a clinical diagnosis of acute tubular necrosis (ATN); since urinary KLK1 originates in the kidney, reduced urinary kallikrein levels may reflect impaired renal function." (PMID 21679467, 2011).
amyotrophic lateral sclerosis (1 paper, 2025). Amyotrophic lateral sclerosis (ALS) is a neurodegenerative disease characterized by progressive muscular paralysis reflecting degeneration of motor neurons in the primary motor cortex, corticospinal tracts, brainstem and spinal cord. "KLK1 is inhibited by several SMIs in the treatment of cardiovascular diseases 53, while the anti-CD14 antibody atibuclimab is administered to patients with amyotrophic lateral sclerosis." (PMID 41049426, 2025).
arterial disease (1 paper, 2021). "The role(s) of Klk1 and Mafb in the phenotypic transformation of Reninnull cells and the arterial disease remains to be determined." (PMID 34762601, 2021).
astrocytoma (1 paper, 2015). "Like KLK6, higher levels of KLK1, KLK7, KLK8, KLK9 and KLK10 were all found to be associated with higher astrocytoma grade." (PMID 26231762, 2015). "Expression of KLK1, KLK6, KLK7, KLK8, KLK9 and KLK10 protein was assessed by immunohistochemical analysis of grade III (n = 8) and grade IV (n = 60, n = 55 for KLK1) astrocytoma samples." (PMID 26231762, 2015). "In this study we determined KLK1, KLK6, KLK7, KLK8, KLK9 and KLK10 protein expression in two independent tissue microarrays containing 60 grade IV and 8 grade III astrocytoma samples." (PMID 26231762, 2015).
candidiasis (1 paper, 2016). Infection with the organism Candida. "Klk1 protects the kidney against acute and chronic disorders in sterile inflammation, but has not been linked to candidiasis or IL-17 signaling." (PMID 27814401, 2016). "Overexpression of Klk1 or treatment with bradykinin rescued IL-17RA-/- mice from candidiasis." (PMID 27814401, 2016).
chromophobe renal cell carcinoma (1 paper, 2018). Chromophobe renal cell carcinoma is a rare subtype of renal cell carcinoma, originating from the intercalating cells of the collecting ducts and macroscopically manifesting as a well-circumscribed, highly lobulated, solid tumor that is usually diagnosed at an early stage. "Chromophobe renal cell carcinoma had increased expression of the following KLKs: KLK1 (32-fold), KLK2 (12-fold), KLK3 (69-fold), KLK4 (234-fold), KLK15 (132-fold), whereas decreased expression of KLK5 (5-fold), KLK6 (13-fold), and KLK7 (26-fold)." (PMID 29707153, 2018). "Our analysis differed and found that KLK1, KLK2, KLK3, KLK4 and KLK15 are highly upregulated in chromophobe renal cell carcinoma." (PMID 29707153, 2018).
Chronic colitis (1 paper, 2025). A chronic inflammatory disease of the large intestine (colon, cecum and rectum). "We used a 2% DSS‐induced mouse model of chronic colitis to investigate the role of KLK1 in enteritis." (PMID 40859429, 2025). "Therefore, we next explored the expression of KLK1 in a DSS‐induced mouse model of chronic colitis." (PMID 40859429, 2025).
chronic obstructive pulmonary disease (1 paper, 2025). A chronic and progressive lung disorder characterized by the loss of elasticity of the bronchial tree and the air sacs, destruction of the air sacs wall, thickening of the bronchial wall, and mucous accumulation in the bronchial tree. "Once released, active KLK1 may stimulate EGF signaling and increase oxidative stress susceptibility, processes implicated in chronic obstructive pulmonary disease (COPD) progression." (PMID 41516101, 2025).
clear cell renal cell carcinoma (1 paper, 2018). "Renal clear cell carcinoma had two KLKs with classification power above the AUC threshold (KLK1: 0.921, KLK6: 0.928)." (PMID 29707153, 2018). "The renal papillary carcinoma and renal clear cell carcinoma had dramatically decreased expression of KLK1 (52-fold and 94-fold), KLK6 (45-fold and 42-fold) and KLK7 (33-fold and 48-fold), respectively." (PMID 29707153, 2018).